ESR1 (estrogen receptor 1)
Diseases named in the same sentence as ESR1 in open-access papers (continued):
Sharing a sentence is not in itself a finding about the gene and the disease.
breast cancer (continued). "ESR1 positive cases (n = 10) in 863 patients tested at the Institute of Pathology, Charité occurred mainly in breast cancer (9/10) and to a lesser degree, in ovarian cancer patients (1/10)." (PMID 40282442, 2025). "TFs also regulate eRNAs, as seen in estrogen receptor 1 (ESR1)-induced eRNAs that maintain transcriptional networks in breast cancer and MyoD enhancer-derived eRNAs that mediate cohesin recruitment during muscle differentiation." (PMID 41373512, 2025). "As a member of the nuclear receptor superfamily, ER exists in two primary isoforms: ERα (encoded by ESR1) and ERβ (encoded by ESR2), with ERα being the predominant and clinically relevant isoform in most hormone-positive breast cancers." (PMID 40983817, 2025). "For instance, circPVT1 serves as a ceRNA to sponge miR-181a-2-3p, thus stabilizing ESR1 mRNA and promoting the genesis of estrogen receptor (ER)-positive breast cancer." (PMID 41041073, 2025). "A study by Bartels reported that approximately 12% of bone metastases from breast cancer exhibited ESR1 mutations, with this frequency rising to 14% in estrogen receptor α-positive cases." (PMID 40075655, 2025). "Correlation heatmap analysis and protein-protein interaction (PPI) network demonstrated strong associations among TNFSF4, TP63, CD24, ESR1, and PRLR, suggesting their potential roles in HR+ breast cancer progression." (PMID 40612672, 2025). "ESR1 is a well-studied receptor known for its involvement in breast cancer and therefore representing a relevant target." (PMID 40001177, 2025). "Later on, ctDNA has been used in advanced breast cancer to detect PIK3CA mutations as resistance to cyclin kinase inhibitors, and, more recently, for the detection of ESR1 mutations." (PMID 40507825, 2025). "We were specifically interested in discovering NR transcription factors in PDAC, similar to what is observed between FOXA1 and ESR1 in breast cancer and between FOXA1 and AR in prostate cancer." (PMID 41168397, 2025). "The clinical significance of reduced ESR1 expression and diminished activity of ESR1‐regulated genes in breast cancers diagnosed in young women remains uncertain." (PMID 40666735, 2025). "Based on this insight, we designed, validated, and implemented a highly sensitive hybrid capture-based NGS assay covering breast cancer-related genes, including ESR1." (PMID 40282442, 2025). "Of note, ESR1 fusions were observed not only in breast cancer (2.3%) but also in endometrial cancer (2.6%) and EOC (1.7%)." (PMID 40711866, 2025). "A phase I/II trial enrolled HER−relapsed breast cancer subjects who had already received CDK4/6is (87%), fulvestrant (71%), or chemotherapy (54%), with 58% of them carrying ESR1 mutations." (PMID 40244377, 2025). "We found that ESR1 expression was also positively correlated with AREG expression in a variety of breast cancer cell lines." (PMID 40422206, 2025). "The active enantiomer of T6I-29, T6I-29-1A, was first assessed for its anti-proliferative activities in Y537S ESR1 breast cancer cell lines compared to clinically relevant compounds and other T6I SERMs." (PMID 38978585, 2024). "Although little is known about the role of CCDC170 in UF, it is recurrently fused with the ESR1 gene in ~14 % of ER+ breast cancers, and patients with such fusion have worse clinical outcomes." (PMID 38326302, 2024). "Fulvestrant still has a role in treating ER-positive HER2-negative metastatic breast cancer, especially those with wild-type ESR1, often in combination with targeted therapy." (PMID 38339371, 2024). "The tumor cells from both sexes had similar transcript levels of estrogen receptor alpha (Esr1), androgen receptor (Ar), and human epidermal growth factor receptors (Erbb2, Erbb3), which are the attributes of the Luminal B breast cancer subtype." (PMID 39684829, 2024).
breast cancer (continued). "This study investigated the expression of MET, ESR1, and ESR2 genes and their association with clinicopathologic characteristics and clinical outcomes in patients with breast cancer." (PMID 39742369, 2024). "In WT ESR1 breast cancer cells T6I-29-1A showed unique effects on genes related to SUMO and SUMOylation." (PMID 38978585, 2024). "We noted that higher levels of macrophage infiltration corresponded to reduced ESR1 or PGR expression in breast cancer and luminal breast cancer." (PMID 38339428, 2024). "Initial studies suggested that SERD (ERα-degrading) activity was required to achieve improved efficacy in Y537S ESR1 breast cancer cells." (PMID 38978585, 2024). "ESR1 is related to the occurrence of gynecological tumors such as breast cancer, endometrial cancer, uterine leiomyoma and so on." (PMID 38533261, 2024). "We and others have reported gene fusion events involving ESR1 in breast cancer, with one of the most common being a recurrent rearrangement between ESR1 exons 1 and 2 and its neighboring gene, coiled-coil domain containing 170 (ESR1-CCDC170)." (PMID 39207954, 2024). "Compared to existing structures of SERMs and SERDs in complex with Y537S ERα LBD, the T6I-29-bound structure is most like raloxifene (RAL), which showed significant anti-transcriptional efficacy in breast cancer cells harboring Y537S ESR1." (PMID 38978585, 2024). "Two of these SNVs (rs2046210 and rs9383590) are located in an enhancer region regulating ESR1 gene expression and have been shown to be functional in breast cancer." (PMID 39200122, 2024). "In light of this, we aimed to assess the expression pattern of ER genes, ESR1 and ESR2, with MET and further explore their association with clinicopathologic features, prognostic factors, and clinical outcomes in breast cancer." (PMID 39742369, 2024). "In the present study while whole blood exposure to hormone-therapy treated breast cancer cells decreased ESR1 expression substantively, corresponding changes in EMT-associated genes indicated higher levels of CDH1 and vimentin in T47D cells than MCF7 cells." (PMID 38233507, 2024). "Five proteins (i.e., EGFR, MAPK3, ESR1, MAPK1, and PTGS2) associated with breast cancer were selected as receptor proteins." (PMID 38794187, 2024). "In breast cancer cells, ESR1 gene modulates S and G2/M phases of the cell cycle but in a ligand-dependent fashion." (PMID 39342193, 2024). "Supportive of this approach, we have found that in preclinical ER+ breast cancer models, vaccination against estrogen receptor alpha (ESR1) gain of function mutants results in anti-tumor responses against ESR1-mutant-expressing murine mammary cancer models." (PMID 39591176, 2024). "Genes such as APP, CDK1, CDK2, and ESR1 were the most frequently observed in this list and have been previously extensively characterized in breast cancer." (PMID 38378612, 2024). "Approximately 75% of primary breast cancers are ESR1-positive, with lymph nodes being the primary metastatic sites for these ESR1-positive breast cancer cells." (PMID 39684286, 2024). "A vast majority of breast cancers (70%) express the prototype oncogene estrogen receptor alpha (ERα, ESR1; herein denoted ER)." (PMID 39207954, 2024). "During breast cancer treatment with estrogen, a cluster of non-coding RNAs is experienced, activating the appropriate ESR1 locus." (PMID 39329990, 2024). "ERα is a major determinant of tumor growth in about 80% of breast cancers in which it controls cell cycle genes such as cyclin D1 (CCND1) and differentiation genes such as the progesterone receptor gene (PGR) and the ERα coding gene itself (ESR1)." (PMID 37989525, 2024).
breast cancer (continued). "Second, we analyzed data from the Cancer Dependency Map project and found that sensitivity to TRPS1 knockout was correlated with sensitivity to ESR1 knockout and significantly enriched among luminal breast cancer cell lines." (PMID 38377146, 2024). "This reduction in ESR1 has also been reported with 17β-estradiol in rat uterus and several breast cancer cell lines, including T47D and MCF7." (PMID 39767718, 2024). "A study concluded that ESR1 mutation correlates with estrogen receptor expression, affecting about 14% of estrogen receptor-positive breast cancer bone metastases." (PMID 38791037, 2024). "For advanced breast cancer patients receiving aromatase inhibitor (AI) and CDK4/6 inhibitor therapy, monitoring the emergence of estrogen receptor 1 (ESR1) mutations holds potential clinical utility." (PMID 39184861, 2024). "In turn, the BRCA1 protein promoted ESR1-gene activation, leading to an increased expression of ER-alpha mRNA and ER protein in breast cancer cell lines." (PMID 39329990, 2024). "ESR1, BRCA1, CTNNB1, and BAX was associated with breast cancer cells proliferation, we further employed Ki67 immunohistochemical staining to evaluate tumor cell proliferation." (PMID 39045563, 2024). "More recently, elacestrant has been approved by the FDA for the treatment of postmenopausal women with ER+, HER2− and ESR1 mutant metastatic or advanced breast cancer with disease progression following more than one line of endocrine therapy." (PMID 39767607, 2024). "GEPIA2 database analysis revealed significant downregulation of PIK3R1, AKR1C3, and EGFR mRNAs in breast cancer tissue, with ESR1 upregulation, pointing to a complex interplay in tumorigenesis and treatment response." (PMID 39204124, 2024). "In 1985, ESR1 was cloned, which is the major driver of the oncogenic process in luminal breast cancers." (PMID 39215346, 2024). "To date, this has been the only study to functionally characterize a set of identified ESR1 fusion proteins, albeit using only one histological subtype of breast cancer." (PMID 39207954, 2024). "In examining the potential utility of the SERM T6I-29-1A in Y537S ESR1 mutant breast cancers, this study revealed a potential new method to modulate DKK1, a paracine factor associated with metastatic progression in many cancers." (PMID 38978585, 2024). "Despite this, 93% of metastasis-specific mutations in putative metastatic driver genes remained undetected within primary tumors, as did 96% of metastasis-specific mutations in known breast cancer drivers, including ERRB2 V777L, ESR1 D538G, and AKT1 D323H." (PMID 38321573, 2024). "These novel endocrine agents have shown activity after fulvestrant and CDK4/6 inhibitors, and on mutant ESR1 in breast cancer." (PMID 38791941, 2024). "Meanwhile, elevated levels of their downstream target genes (ESR1 and CDKN1A) were associated with poor prognosis of breast cancer patients." (PMID 38254989, 2024). "Estrogen Receptor 1 (ESR1) is an attractive drug target for treating breast cancer, myocardial infarction, and migraine." (PMID 38626166, 2024). "For example, ESR1 is the target of raloxifene, toremifene, tamoxifen, and fulvestrant which are reported to prevent or treat breast cancer." (PMID 39175079, 2024). "Estrogen receptor 1 (ESR1) is a key transcription factor for responding to tamoxifen treatment in ESR1‐positive breast cancer." (PMID 38881534, 2024). "According to the report of breast cancer, LINC01116 competitively combines with miR‐145 to regulate ESR1, which is a novel prognostic biomarker of breast cancer." (PMID 39648148, 2024). "In terms of genetics, genetic analysis of CTC clusters in breast cancer showed that CTC clusters were significantly associated with cadherin 1 (CDH1) and ESR1 Y537S and D538G mutations." (PMID 38427120, 2024).
breast cancer (continued). "Taken together, these findings identify NPY1R as one of the most consistent and universal upregulated targets in ESR1 mutant breast cancer, likely driven by the constitutive activation of mutant ER and their increased binding activity at this gene locus." (PMID 39702552, 2024). "Various studies have published different ESR1 amplification frequencies in breast cancers, ranging from 0% to 75%." (PMID 39329990, 2024). "Especially, the gene expression of estrogen receptor-α (ESR1) shows a strong positive correlation with the age of breast cancer patients at diagnosis." (PMID 39405593, 2024). "On the other hand, the migratory subtype showed shared characteristics with Luminal A and Normal-like classification, as they had low expression of known breast cancer markers such as ESR1, PGR and ERBB2." (PMID 38892065, 2024). "We also confirmed that HR+ breast cancer cell-lines were significantly more sensitive to the drugs targeting ESR1 than TNBC samples (P-value = 3.46E-04) using drug sensitivity data of GDSC." (PMID 38622359, 2024). "Both the ESR1 and ERα expression were higher in breast cancer tumors than in normal tissues, based on the differential gene expression in clinical patients." (PMID 39202273, 2024). "For instance, triple-negative breast cancer, which lacks ESR1 expression, has the poorest prognosis among the five molecular subtypes of breast cancer." (PMID 39684286, 2024). "A significant positive correlation between IRF6 and ESR1 expression was found in Basal and Luminal A subtypes, giving a good marker for breast cancer patients." (PMID 39765744, 2024). "Accordingly, knocking down ESR1 expression limits L1 expression in the breast cancer cell line MCF-7." (PMID 38309261, 2024). "Among them, EGFR, MAPK1, MAPK3, PTGS2, and ESR1 were specifically evaluated for breast cancer treatment." (PMID 38794187, 2024). "In ERα‐positive breast cancer, PSF associates with the pre‐mRNAs of oncogenic genes, such as ERα (ESR1) and Sec1 family domain containing 2 (SCFD2), to sustain the mRNA level by post‐transcriptional regulation." (PMID 39155453, 2024). "Recently, in tamoxifen-responsive, early-stage breast cancers, focal ESR1 gene amplification was a powerful predictor for the long-term tumor-free survival of patients." (PMID 39329990, 2024). "Here, we present a robust genomic analysis of resistance to fulvestrant in ESR1-mutant breast cancer using paired circulating tumor DNA sequencing in patients treated with fulvestrant in the plasmaMATCH study." (PMID 37982575, 2024). "GATA3 is expressed in some breast cancers and functions as a coregulator of ESR1 (encoding ERα) gene transcription." (PMID 39336822, 2024). "Among other examples, functional roles of lncRNA TMPO-AS1 in breast cancer progression via the stabilization of ESR1 mRNA expression have been reported." (PMID 39199690, 2024). "Three quarters of all breast cancers express the estrogen receptor (ER, ESR1 gene), which promotes tumor growth and constitutes a direct target for endocrine therapies." (PMID 38519482, 2024). "Despite the elevated circulating estrogen levels commonly observed in obese individuals, the strong reduction in ESR1 expression observed in luminal breast cancer mammospheres after ELIT exposure is consistent with a previous study in adherent cells." (PMID 39767718, 2024). "Most breast cancers express the estrogen receptor (ER; ESR1 gene), a steroid hormone receptor that acts as a transcription factor once bound by estrogens." (PMID 38519482, 2024). "It is already known from breast cancer research that the transcriptional regulation of ESR1 can also be controlled by various extrinsic factors." (PMID 39456226, 2024). "When MCF-7 and T-47D breast cancer cell lines were cultured in 1% O2 for 8–24 h, ESR1 mRNA was significantly reduced as a consequence of transcriptional repression in a HIF-1α-dependent manner." (PMID 39282472, 2024).
breast cancer (continued). "If, as our data suggest, DKK1 expression can be modulated by a SERM and the glycoprotein contributes to metastatic progression, then this study has revealed a new therapeutic axis that can be exploited to treat endocrine-resistant ESR1 mutant breast cancer." (PMID 38978585, 2024). "For example, a recent breast cancer GWAS found a strong signal in the ESR1 locus which is the target of tamoxifen, a widely used drug for breast cancer treatment." (PMID 38947022, 2024). "It is currently in clinical trials (ELAINE trials) for treatment of advanced stage ESR1 mutant breast cancer." (PMID 38978585, 2024). "Hypoxia-mediated epigenetic modification of the ESR1 gene has significant implications on the expression of the ERα, and desensitisation of breast cancer cells to anti-oestrogen therapy through ESR1 gene silencing." (PMID 39282472, 2024). "LY3484356 exhibited substantial tumor growth inhibition and tumor regressions in wild-type ESR1 breast cancer xenograft, as well as ESR1 mutant breast cancer PDX models." (PMID 39767607, 2024). "We identified 1,350 interactions between 265 TFs and the promoters of 108 cancer genes, and leveraged our promoter library to study disordered regions in the breast cancer–related TF estrogen receptor ɑ (ESR1)." (PMID 39013578, 2024). "DeePathNet was able to highlight known biomarkers when predicting breast cancer subtypes, including ESR1, ERBB2, and the FOXM1 network pathways." (PMID 39530738, 2024). "In contrast to our results, a high ESR1 expression was a strong predictor of tamoxifen benefits in ER+ breast cancer in the National Surgical Adjuvant Breast and Bowel Project (NSABP) B-14 trial." (PMID 37773134, 2023). "ESR1-CCDC170 and ESR1 exon 6, have been reported to result in estrogen resistance and metastatic transformation in Luminal B breast cancer." (PMID 37744342, 2023). "In the TCGA breast cancer cohort, most of the BMPs were significantly correlated with ESR1 (ERα) and ESR2 (ERβ) with a contrasting pattern." (PMID 37333824, 2023). "In those cases, the expression of breast cancer markers, such as ESR1 and ERBB2, was relatively low in the HER2-2 and luminal-3, -6, and -11 cases." (PMID 37759508, 2023). "For breast cancer patients, known oncogenes and tumor suppressor genes such as ESR1, KRAS, PIK3CA, PIK3R1, FAT1, and MED12 were consistently identified in both ctDNA and tumor WES across patients." (PMID 37878600, 2023). "For use in breast cancer patients, the full exonic territory of HER2 and ESR1 was included to allow for mutation as well as HER2 amplification detection." (PMID 37444554, 2023). "Other ESR1 targets, such as lasofoxifene and H3B-5942, have proved superior to fulvestrant in inhibiting metastatic processes in breast cancer xenografts harboring Y537S and D538G ESR1 mutants." (PMID 36980614, 2023). "Although genes that are particularly specified for breast cancer, such as ESR1, PGR, HER2, EGFR, and AR are highly correlated in mRNA-protein expression, nearly 50% of gene expressions are not consistent with their protein levels both in tumors and cell lines." (PMID 37408196, 2023). "The literature is limited on ESR and circadian rhythm; so far it seems there is a link between ESR1-induced CLOCK expression in breast cancer cells." (PMID 36985125, 2023). "DSCAM-AS1 functions as a microRNA sponge for miR-130a, which is similarly sponged by DSCAM-AS1, targets the 3′-UTR of ESR1 that is a crucial regulator of breast cancer progression and metastasis." (PMID 37395734, 2023).